CTLA4 (cytotoxic T-lymphocyte associated protein 4)
Diseases named in the same sentence as CTLA4 in open-access papers (continued):
Sharing a sentence is not in itself a finding about the gene and the disease.
tumor (continued). "In a mouse model inoculated with tumor cells on the bilateral flank, the experimental data showed the local irradiation group knocked down the expression of Trex1 and the administration of anti-CTLA-4 restored the ability of abscopal effect induction, in contrast to the Trex1 upregulated group." (PMID 32992835, 2020). "Moreover, this anti-tumor effect can synergize with anti-CTLA4 or anti-PD1 therapy, thus may serve as a therapeutic target to further improve the efficacy of immune checkpoint blockade responders." (PMID 32477338, 2020). "Thus, superior results were obtained for the administration of anti-CTLA4 immunotherapy followed by hypofractionated radiotherapy, but the anti-PD-L1 therapy demonstrates the maximum potential of radio-sensitization of the tumor in case of concurrent administration." (PMID 33374739, 2020). "The hosts’ s own microbiota can be utilized to treat cancer, for example Bifidobacterium which is facilitates PD-L1 and CTLA-4 blockade which unmask the tumor cell and promotes T-cell killing of tumor cell and may serve as “a key orchestrator of cancer therapy”." (PMID 32257138, 2020). "In addition, a hypoxic acidic environment can also induce the upregulation of PD-L1 on tumor cells and CTLA-4, TIM-3, and PD-L1 on the surface of immunosuppressive cells, which help tumor cells escape the killing mediated by T cells and NK cells and ultimately promote tumor development." (PMID 32850400, 2020). "From an “oncological” point of view, the most important feature of CTLA-4 is its engagement in evading immune surveillance by cancer cells, since cancer cells may employ mechanisms leading to upregulation of CTLA-4 and as consequence repression of immune response toward tumor cells." (PMID 33519815, 2020). "However, we found no positive correlation between PD-1+ and CTLA-4+ T cells (for Th, rs = 0.022, p = 0.870 and for Tcyt, rs = −0.172, p = 0.206), suggesting that PD-1 and CTLA-4 may define different populations of T cells and different tumours." (PMID 33228141, 2020). "PD-L1, belonging to the CD28+ cytotoxic T-lymphocyte associated protein 4 (CTLA-4) receptor subfamily, is an extremely important costimulatory molecule in immune response, and it displays a leading role in inducing immune tolerance in the microenvironment of the tumor." (PMID 32884946, 2020). "Thus, there is an increased expression of the immune inhibitory molecules PD-L1 and CTLA-4 in COSCC tumor cells that also display active EMT signaling, suggesting that COSCC patients could potentially benefit from immune checkpoint inhibitor therapies." (PMID 33142242, 2020). "CTLA-4 blockade affects the immune priming phase occurring in the lymph node and reduces regulatory T lymphocytes (Treg)-mediated suppression of effector T cells, while PD-1 blockade affects the effector phase in the tumor and restores the immune function of “exhausted” T cells." (PMID 31783782, 2019). "In addition to their immune suppressive function, they may be a target for antibody dependent cellular cytotoxicity (ADCC) by ipilimumab due to their high expression levels of CTLA-4 that make Tregs sentinels for ICI-mediated anti-tumor responses." (PMID 31192215, 2019). "In order to understand whether CTLA4 is expressed in NSCLC, whether tumour cell‐intrinsic CTLA4 plays a role in tumorigenesis, we examined the CTLA4, PD‐1, PD‐L1 expression levels in multiple NSCLC cell lines with different oncogenic mutations and in the tissue samples from NSCLC patients." (PMID 30378264, 2019). "In addition, PD-L1-expressing DCs may also drive the progression of naïve, PD-1-expressing CD4 Tregs to the mature, immunosuppressive phenotype, favoring co-operative impairment of anti-tumor host defenses due to co-expression of CTLA-4 and PD-1 by Tregs." (PMID 31616428, 2019). "Thus, CTLA-4 is critical for self-tolerance, attenuating autoimmunity and anti-tumour immunity." (PMID 31300681, 2019).
tumor (continued). "In the exceptional responder in our series (patient 3), the tumor mutational burden was surprisingly low, thus one may not have anticipated the remarkable response to extremely low dosing of anti-CTLA-4 antibody." (PMID 31395100, 2019). "Tumor inflammation could lead to an antitumor immunity deficiency by involving T-helpers and T-regulating lymphocytes, notably via immune checkpoints (PD1–PDL1, CTLA4) and cytokines, thus promoting tumor growth." (PMID 30917620, 2019). "Blocking antibodies, designed to interfere with checkpoint molecules CTLA-4 and PD-1/PD-L1 and counteract these immune suppressive mechanisms, have shown significant success in promoting immune responses against cancer and can result in tumor regression in many patients." (PMID 30941125, 2019). "Thus, to boost the effect of the vaccine alone, one could benefit from additionally targeting factors of the tumor escape mechanism, including the expression of T cell inactivating proteins, such as PD-1/PD-L1 or CTLA-4." (PMID 30858929, 2019). "The CTLA-4 antibodies have a distinct mechanism of action targeting different receptor interactions from PD-L1/PD-1 inhibitors that may also impact a different phase of the anti-tumor immune response." (PMID 31731749, 2019). "In addition several studies have shown that CTLA-4 expression inhibits anti-tumor immune responses." (PMID 31192129, 2019). "The 4T1 tumor cells are poorly immunogenic and refractory to immune therapies, although the combination of anti-PD-1, anti-CTLA-4 ICB with epigenetic modulators could have a therapeutic benefit curing more than 80% of 4T1 tumor bearing mice via eliminating MDSCs." (PMID 31881770, 2019). "Wnt pathway regulation may play a role in this lack of response, as tumor-intrinsic, active β-catenin signaling in human melanoma has been associated with resistance to anti-CTLA4 and anti-PD-L1 antibodies due to T cell exclusion." (PMID 31167446, 2019). "DMAbs can also conceptually simplify combination therapies, allowing administration of anti-CTLA4 and anti-PD-1 combinations with a single injection or providing simplified immune combinations for study such as cancer vaccines or DMAbs targeting other tumor targets." (PMID 30713599, 2019). "Biological rationale encouraged the synergy of CTLA-4 inhibition, which favours the development of an active immune response at the level of T-cell proliferation, with PD-1 inhibition, which modulates the immune response at the level of the tumour micro-environment." (PMID 30987368, 2019). "Likewise, whereas CTLA-4 checkpoint blockade is used to increase anti-tumor immunity; this approach could be contraindicative in obese patients due to excess activation of the chronic low-grade inflammation." (PMID 31475003, 2019). "Further viruses were constructed based on this virus which additionally express an anti-CTLA-4 antibody or immune co-stimulatory pathway activating ligands, each of which is expected to act at the site and time of immune response initiation in the injected tumor and draining lymph nodes." (PMID 31399043, 2019). "Furthermore, IFNγ (TME) activates the expression of CTLA-4 in the tumor microenvironment." (PMID 31192129, 2019). "CTLA-4 and PD-1 are up-regulated when T cells become activated, which in the case of PD-1 has also been linked to neo-antigen specificity, and since the introduction of ICI, we know that selectively inhibiting these immune checkpoints can result in unprecedented anti-tumor activity." (PMID 30852622, 2019). "Furthermore, a BiTE designed to simultaneously target two immune checkpoints on T-eff cells, such as CTLA-4 and PD-1, may improve tumor killing and increase efficacy since dual therapies of anti-PD-1 and anti-CTLA-4 have proven effective." (PMID 30941125, 2019). "However, combining RT and IT-IC, RT and anti-CTLA-4, or RT, IT-IC and anti-CTLA-4 did not cause any significant tumor growth inhibition over that seen with RT alone." (PMID 31810498, 2019).
tumor (continued). "Thus, CTLA-4 blockade potentiates effective immune responses against tumor cells." (PMID 31847387, 2019). "They proposed that anti-CD137 and interleukin (IL)-2Fc loaded nanoparticles may have a synergistic effect in combination with the administration of well-tolerated immunotherapy agents, e.g., anti-CTLA-4 or anti-PD-1 which are known to enhance tumor regression in humans." (PMID 30941175, 2019). "Therefore, since CTLA-4 and PD-1 inhibitors exert anti-tumor effects through different mechanisms of action, combining these agents could potentially lead to more efficacious treatments." (PMID 30941125, 2019). "In addition to PD-1/PD-L1 and CTLA-4 antibodies which are already established in tumor immunotherapy, immune checkpoints such as LAG-3 or BTLA are emerging, which may have the potential to enhance T-cell responses alone or in combination with PD-1 blockers." (PMID 31332464, 2019). "Thus, clinically effective anti-CTLA-4 mAb causes tumor rejection by mechanisms that are independent of checkpoint blockade but dependent on the host Fc receptor." (PMID 29472691, 2018). "In 2008, a pilot clinical trial with anti-CTLA-4 (ipilimumab) treatment on 12 early UBC patients before radical cystectomy showed that the expression of inducible co-stimulator (ICOS) had increased significantly in CD4+ T-cell subpopulation from both tumor tissues and peripheral blood." (PMID 29358573, 2018). "However, following treatment, tumor cells had increased expression of PD‐L1 and effector T cells had increased expression of CTLA4, suggesting immune checkpoint blockade in conjunction with CSF1R blockade may have a synergistic effect." (PMID 30003190, 2018). "Furthermore, tumor infiltrating T cells in the mouse cohort that received hexatherapy have higher proliferative capacity (Ki67+) and have significantly less exhausted phenotype showing less PD-1 and CTLA-4- expression." (PMID 30400835, 2018). "Cytotoxic T lymphocyte-associated antigen-4 (CTLA-4) antibody primarily blocks inhibitory signaling of T cell priming and activation while programmed cell death protein 1/programmed cell death ligand 1 (PD-1/PD-L1) antibody primarily recovers attenuated anti-tumor immune response in tumor bed." (PMID 30473928, 2018). "Furthermore, curcumin plus anti-CTLA4 was effective in inhibiting tumor growth." (PMID 29535627, 2018). "Syngeneic mouse tumour models have frequently been used to profile immune responses in tumours, CRL have optimized and profiled existing check-point inhibitors to support immuno-oncology drug discovery using mouse and rat antibody variants of anti-CTLA4 and anti-PD1." (PMID 30400822, 2018). "We found that 77.4% of the clustered tumor specimens evade through transforming growth factor-beta (TGF-β) immunosuppression, 57.7% through decoy receptor 3 (DcR3) counterattack, 48.0% through cytotoxic T-lymphocyte-associated protein 4 (CTLA4), and 34.3% through programmed cell death-1 (PD-1)." (PMID 30513096, 2018). "However, CTLA-4 expression was also detected on multiple tumor cells including NSCLC." (PMID 30577587, 2018). "Our pre-clinical data support a unifying hypothesis in which both hIgG1 and hIgG2 anti-CTLA-4 mAbs employed in the clinic act to promote preferential depletion of tumor-infiltrating Treg cells and increase the intra-tumoral Teff/Treg cell ratio associated with tumor rejection." (PMID 29576375, 2018). "Thus, SP-D, by increasing the expression of CTLA-4, may contribute to the inhibition of the anti-tumor immune responses." (PMID 30127783, 2018). "Immunomodulatory cancer immunotherapy using cytotoxic T lymphocyte antigen 4 (CTLA-4) or programmed cell death 1 receptor (PD-1)-specific checkpoint blockade provides substantial clinical benefits for a minority of cancer patients by unleashing their own anti-tumor immunity." (PMID 29348598, 2018).
tumor (continued). "Antibodies that block CTLA-4 extrinsic and intrinsic immune regulation (ipilimumab, tremilimumab) result in clinical responses that correlate with the emergence of new high-avidity T cell clones and anti-tumor T cell clones, suggesting that the site of action is in lymphoid tissue." (PMID 30376867, 2018). "Moreover, the transcriptional upregulation of CTLA-4 in tumor tissue might be under the control of both DNA hypomethylation and lower H3K27me3 enrichment, while DNA hypomethylation and lower H3K9me3 enrichment regulate TIGIT expression." (PMID 30081950, 2018). "Interestingly, a blockade of CTLA4 in preclinical murine cancer models restores effector T-cells and decreases Tregs in melanoma and colorectal cancer, demonstrating the important role of this molecule in tumor immune evasion." (PMID 29301364, 2018). "However, the anti-tumor effect of CTLA-4 blockade alone is limited, and monotherapy may lead to serious autoimmune-related side effects such as dermatitis, colitis, hepatitis, and hypophysitis." (PMID 30115069, 2018). "CTLA-4 is expressed on T lymphocytes and, by binding B7 receptors on antigen-presenting cells (APCs), determines inhibition of T-cell activation at the priming phase of the immune response, when a naïve T lymphocyte recognizes tumor antigens for the first time." (PMID 30545122, 2018). "In biliary tract cancers it has been observed that the deregulation of immunomodulatory transcripts in peritumoral areas may create an immunosuppressive milieu that facilitates tumor recurrence, possibly through the activation of the cytotoxic T lymphocyte antigen-4 (CTLA4) axis." (PMID 30249019, 2018). "We hypothesize that this approach is better suited to immunostimulatory agents that act at low doses rather than drugs that block inhibitory receptors (e.g., anti-PD-1, anti-CTLA-4), which may require high doses to fully block target receptors on tumor-infiltrating immune cells." (PMID 29295974, 2018). "For example, ipilimumab is a humanized IgG1 recombinant antibody that can mediate antibody-dependent cellular cytotoxicity (ADCC) and complement-mediated cellular cytotoxicity, and may deplete tumor-infiltrating Tregs, which have elevated expression of CTLA-4 compared with Teff cells." (PMID 30376867, 2018). "The investigators found that poor tumor perfusion, as measured by multiparametric methods, correlated with high expression levels of vascular endothelial growth factor A (VEGFA) and immune checkpoints, cluster of differentiation 274 (CD274) and cytotoxic T-lymphocyte-associated-protein 4 (CTLA4)." (PMID 30591628, 2018). "Many of these studies also analyzed tumor samples upon progression and found no recurrent genetic mutation, which could mean that resistance to anti-CTLA-4 is patient specific." (PMID 29896449, 2018). "Over-expression of coinhibitory molecules, such as CTLA-4, PD-1, and Tim-3, often results in the functional inhibition or exhaustion of T cells, reversing which by antibodies gives rise to the promising therapeutic modality in tumor, called checkpoint immunotherapy." (PMID 29593314, 2018). "Thus, the use of CTLA-4 blockade may affect intratumoral immune responses by enhancing Teff cells function and/or depleting tumor-infiltrating Treg cells." (PMID 29482595, 2018). "Tumor cells express programmed cell-death 1 ligand (PD-L1) and the cluster of differentiation 86 (CD86) protein binds to immune-checkpoint receptors programmed cell-death protein 1 (PD-1) and cytotoxic T-lymphocyte-associated protein 4 (CTLA-4) of CD8+ T-cell to inhibit host immune responses." (PMID 29301348, 2018). "In anti-CTLA-4 treatment, the diversity of TCR repertoire in PBL increased after treatment, and in anti-PD-1 treatment, patients with improved survival showed high pre-treatment TCR repertoire diversity and greater post-treatment expansion of tumor-associated clones in PBL." (PMID 30733724, 2018). "CTLA-4 on tumor cells might also act as local mechanism of immune escape." (PMID 30108594, 2018).
tumor (continued). "The successful co-targeting of PD-1 and CTLA-4 and encouraging results obtained in preclinical models that combined PD-1 antibodies with other immune checkpoint inhibitors has fostered strategies to combine immune checkpoint inhibitors to enhance anti-tumor responses in patients with cancer." (PMID 30233564, 2018). "Moreover, the vast amount of preclinical data also suggested that the anti-tumor activity of combination therapy with CTLA-4 plus PD-1/PD-L1 checkpoint inhibitors may have superior outcomes compared to CTLA-4 or PD-1 monotherapy." (PMID 29769148, 2018). "A complete tumor eradication was reported when L19-IL-2 was administered in combination with CTLA-4 blockade in two syngeneic immunocompetent mouse models of teratocarcinoma and colon carcinoma; in the latter model, responder mice to this combination treatment were resistant to tumor re-challenge." (PMID 30619269, 2018). "Thus, uncovering other predictive biomarkers for immune blockade responses—such as CTLA-4/PD-1 expression on immune infiltrate and tumor cells, TILs, and circulating MDSCs and lymphocytes—should be prioritized in order to improve the efficacy of personalized treatments of patient." (PMID 30191140, 2018). "Thus, HLA-G is capable of inhibiting all actors of anti-tumor responses and in contrast to both CTLA-4 and PD-1, of blocking all stages of such an anti-tumor response, from the APC activation and effector priming, to the function of a fully activated cytotoxic T cell or NK cell." (PMID 30237859, 2018). "Anecdotal evidence suggested that in patients treated with anti CTLA-4 mAb(ipilimumab) and subsequent palliative radiotherapy objective responses were detectedoutside the irradiation field, concurrent with increases in the titer of antibodiesagainst the shared tumor antigen NY-ESO1." (PMID 29552325, 2018). "As IFN-γ-mediated upregulation of PD-L1 has been shown to be a mechanism of adaptive immune tolerance, it remains possible that PD-1/PD-L1 blockade could potentially enhance the antitumor activity of a-CTLA4-TGFβRII over a more extended treatment period or in other tumor models." (PMID 29467463, 2018). "Altered expression of indoleamine 2,3 dioxygenase (IDO) in tumor cells or alternatively polarized/pro-tumorigenic macrophages can affect the local availability of tryptophan and kynurenine metabolites limiting T-cell function and also possibly modifying downstream effects of CTLA-4 signaling." (PMID 30514385, 2018). "This work presents an immune‐stimulating UCNP‐based PDT strategy in combination with CTLA‐4 checkpoint blockade to effectively destroy primary tumors under light exposure, inhibit distant tumors that can hardly be reached by light, and prevent tumor reoccurrence via the immune memory effect." (PMID 29658188, 2018). "Further study, nevertheless, showed solely MDSCs depletion could not re-sensitize tumour cells towards BRAF inhibitor treatment, while combination treatment with immunotherapies anti-CTLA-4 and anti PD-1 elicited tumour cells to immunotherapy-triggered cancer cell death." (PMID 29455663, 2018). "In 31 HCC patients, it was found the addition of anti-CTLA-4 antibody resulted in an increase in the frequency of tumor-associated antigens (TAA)-specific cytotoxic T cells in 60% of HCC patients, accompanied with enhanced antitumor effect of tumor-specific T cells." (PMID 29843754, 2018). "However, tumor cells express B7 that bind to CTLA-4 and inhibit these cytotoxic effects." (PMID 30366424, 2018). "Thus, the reduced frequency of highly activated CTLA-4+ Ki-67high Tregs in the tumours of IL-2WTFc-treated mice may provide a basis for improved antitumour responses." (PMID 28497796, 2017). "Furthermore, CTLA-4 also leads to down-regulation of T-cell response and peripheral tolerance, diminishes the generation of effective antitumor response, and thus brings tumor immune tolerance." (PMID 28099147, 2017).